MAP4K4 (mitogen-activated protein kinase kinase kinase kinase 4)
Diseases named in the same sentence as MAP4K4 in open-access papers (continued):
Sharing a sentence is not in itself a finding about the gene and the disease.
tumor (continued). "By randomly assessing the potential target genes in the tumor samples, we have found that up-regulated SOX9, RASA1, CEP55 and MAP4K4, the target genes of miR-582, might play important roles in LUAD tumorigenesis." (PMID 33510968, 2021). "To gain insight in MAP4K4 protein expression in human MB tumor tissue, we scored MAP4K4 expression levels by immunohistochemistry (IHC) into negative, low, moderate and high in a MB tissue micro array (TMA) containing 68 human tumor samples and 7 cb controls." (PMID 29796184, 2018). "The long version of MAP4K4 and MAP4K4 cloned from tumor cells, but not the short version of MAP4K4, also contain proline-rich regions." (PMID 27800153, 2016). "MAP4K4 is overexpressed in many tumor cell lines, has been shown to modulate cellular transformation, invasion, and adhesion, and is highly expressed in GBM tumor samples." (PMID 24163766, 2013). "Since MAP4K4 also belongs to the Ste20 family and is activated by TNFα to participate in the JNK signaling pathway, we hypothesized that MAP4K4 may act upstream of MLK3 to promote tumor development." (PMID 36292671, 2022). "Thus, non-autonomous functions of MAP4K4 in endothelial cells likely contribute to tumor progression by increased vascularization and an accentuated response to the inflammatory cytokine TNFα." (PMID 36568222, 2022). "Depletion of STRN3 but not of MAP4K4 reduced tumor cell growth in the cerebellum tissue." (PMID 35941177, 2022). "As MAP4K4 also belongs to the Ste20 family, and like MLK3 is activated downstream of TNFα and feeds into JNK signaling, we hypothesized that MAP4K4 might act upstream of MLK3, thereby enhancing tumor development." (PMID 34511598, 2021). "Thus, the inhibitors of MAP4K4 promote cardiomyocyte resistance to DOX without confounding effects on tumour cell death." (PMID 32694738, 2020). "At the present study, we found overexpression of miR-141 could inhibit proliferation, migration, tumor-forming and invasive potential of CRC cells in vitro and mitogen-activated protein kinase kinase kinase kinase 4 (MAP4K4) was verified as a directed target of miR-141." (PMID 30429233, 2018). "We previously observed an increased MAP4K4-dependent invasiveness in SHH MB tumor cells exposed to 1–2 Gy22, suggesting that the irradiation-induced increase in cell invasion observed could in part be mediated by CLSTN1 downregulation via increased MAP4K4 activity." (PMID 39762313, 2025). "In addition, non-autonomous functions of MAP4K4 in the tumor stroma including the regulation of endothelial cells during vascular development, endothelial cell motility, T cell activation and of glucose up-take and lipogenesis may contribute to tumor growth and progression." (PMID 36568222, 2022). "Moreover, MAP4K4‐mediated T227 phosphorylation is essential for enhancing HCC metastasis because non‐phosphorylatable G3BP2‐T227A fails to induce EMT signaling, tumor cell migration, and invasion." (PMID 38639383, 2024).
cardiovascular disease (11 papers, 2015 to 2025). "MAP4K4 is a member of the Ste20 family of kinases, which have been broadly reported to participate in multiple cardiovascular diseases." (PMID 38724987, 2024). "The role of MAP4K4 in immunity, inflammation, metabolic and cardiovascular disease has been recognized." (PMID 27800153, 2016). "For detailed information regarding MAP4K4 in immunity/inflammation and metabolic/cardiovascular diseases, we refer the reader to two excellent reviews." (PMID 27800153, 2016). "All these data strongly support the idea that MAP4K4 may be a novel therapeutic target for the treatment of cardiovascular disease." (PMID 40913245, 2025). "Besides, the important multiple roles of MAP4K4 in immunity, neuropathology, metabolic, inflammation, and cardiovascular disease had been widely recognized." (PMID 36922678, 2023). "Together, these data strongly support the idea that MAP4K4 may be a novel therapeutic target for the treatment of cardiovascular disease." (PMID 26688060, 2015).
metabolic disease (6 papers, 2019 to 2025). A congenital disorder (due to inherited enzyme abnormality) or acquired (due to failure of a metabolically important organ) disorder resulting from an abnormal metabolic process. "Nme7 interacts directly with several entities related to lipid handling and insulin sensitivity, including the established nodes of metabolic diseases: the mitogen-activated protein kinase kinase kinase kinase 4 (Mapk4k4) and hepatocyte nuclear factor 4 (Hnf4)." (PMID 34356103, 2021).
infection (4 papers, 2013 to 2021). The state of being infected such as from the introduction of a foreign agent such as serum, vaccine, antigenic substance or organism. "To extend our observations, which were obtained with the immortalized endothelial cell line HuAR2T, to primary endothelial cells, we investigated the role of MAP4K4 in the invasiveness of human umbilical vein endothelial cells (HUVECs) following their infection with rKSHV.219." (PMID 24244164, 2013). "Following infection and treatment, cardiomyocyte extracts were immunoblotted for the FLAG epitope or MAP4K4 immunoprecipitated for kinase activity assays." (PMID 34032269, 2021). "Similar to KSHV-infected HuAR2T cells, expression of COX-2 increased after infection of HUVECs with KSHV and silencing of MAP4K4 by siRNA reduced COX-2 levels in KSHV-infected primary endothelial cells." (PMID 24244164, 2013). "Adenoviral infections of cardiomyocytes did not produce uniform expression of the different forms of MAP4K4 despite using the same multiplicity of infection." (PMID 34032269, 2021). "We also observed that after infection with KSHV, MAP4K4 protein levels were moderately increased." (PMID 24244164, 2013). "On day 5 after infection, KSHV-infected HUVECs showed a markedly increased invasiveness compared to uninfected cells, and this increased invasiveness depended on the expression of MAP4K4, since silencing of MAP4K4 with siRNA reduced their invasiveness to background levels." (PMID 24244164, 2013). "In addition, genes that targeted kinases (MAP2K7, MAP4K4 and MAPK14) were downregulated in the first 15 min of CHIKV infection, although MAP2K7 and MAP4K4 were subsequently found to be upregulated after 30 min and 120 min of infection." (PMID 23409203, 2013).
neurodegenerative disease (2 papers, 2022). A disorder of the central nervous system characterized by gradual and progressive loss of neural tissue and neurologic function. "Inhibitors of MAP4K4 are currently being developed in clinical trials as a candidate treatment for neurodegenerative diseases by increasing the activity of motor neurons extracted from the induced pluripotent stem cells (iPSCs)." (PMID 36497065, 2022). "The notion that MAP4K4 may be a new target for the treatment of neurodegenerative diseases was already previously postulated in a study using optimized small molecule compounds based on the neuritogenic pyridones (militarinone-inspired 4-hydroxy-2-pyridone) collection." (PMID 36568222, 2022).
adenocarcinoma (1 paper, 2023). A common cancer characterized by the presence of malignant glandular cells. "This phenomenon might be attributed to the different expression levels of MAP4K4 in pancreatic epithelial cells and adenocarcinoma cells." (PMID 36683274, 2023).
MAP4K4 also shares sentences with these, for which no sentence is quoted: pancreatic ductal adenocarcinoma (4 papers); diabetic cardiomyopathy (3); acute myeloid leukemia (2); colon cancer (2); Impaired glucose tolerance (2); multiple myeloma (2); non-small cell lung carcinoma (2); psychiatric disease (2); schizophrenia (2); actinic keratosis (1); asthma (1); autoimmune (1); bladder cancer (1); bronchiolitis (1); Cirrhosis (1); congenital heart disease (1); depression (1); emphysema (1); ganglioglioma (1); gastric tumor (1); Glucose intolerance (1); idiopathic pulmonary fibrosis (1); immune diseases (1); ischemic cardiomyopathy (1); leukemia (1); metastatic prostate carcinoma (1); motor neuron degeneration (1); neurodevelopmental disorder (1); oral cancers (1); rectal cancer (1).
A further 3 diseases each share a sentence with MAP4K4 in 1 paper.